SOX2 (SRY-box transcription factor 2)
Diseases named in the same sentence as SOX2 in open-access papers (continued):
Sharing a sentence is not in itself a finding about the gene and the disease.
breast cancer (continued). "Specifically, SOX2 is reported as a lineage-survival oncogene in squamous cell carcinoma of the lung and its over-expression is associated with tumor progression and poor clinical outcome in breast cancer." (PMID 24404135, 2014). "Furthermore, SOX2 has been observed in 43% of basal breast carcinomas which was associated with a less differentiated phenotype." (PMID 22070920, 2011). "Therefore, inhibiting SOX2 expression may decrease the malignant characteristics associated with breast cancer, such as invasion, migration, proliferation, stemness, and chemoresistance." (PMID 37542193, 2023). "PCA decreased the CD44high/CD24low and ALDH1+ subpopulations of breast cancer cells and decreased the protein levels of Akt, pAkt, and Sox2." (PMID 40076435, 2025). "This flavanone was found to inhibit breast cancer stem cells through the inhibition of colony and mammosphere formation, reduced levels of transcriptional factors (Oct2, Nanaog, Sox2), and the inhibition of STAT3 signaling pathways." (PMID 39859345, 2025). "ECM-mediated changes in the expression and/or cellular localization of SOX2, OCT4 and KLF4 are associated with prostate and breast cancer." (PMID 39611488, 2025). "SOX2-overexpressing breast cancer cells activated NF-κB-CCL1 signaling to recruit Tregs which in turn upregulated the stemness of breast cancer cells evident by increased ALDHhigh population and enhanced stemness gene expression." (PMID 39990669, 2025). "Breast cancer: SOX2 expression was elevated in 60% of breast cancer cases (p < 0.001), particularly in HER2-positive subtypes." (PMID 40674376, 2025). "The average diagnosis age of breast cancer patients with high SOX2 expression (SOX2high) is younger than that of patients with low SOX2 expression (SOX2low)." (PMID 40959920, 2025). "SOX2, YB1, and FOXQ1 are all transcription factors associated with signaling pathways that are constitutively activated in breast cancer, particularly TNBC, including Wnt/B-catenin, Hedgehog, and Notch, which regulate the maintenance and survival of CSCs." (PMID 40432134, 2025). "In breast cancer, SOX2 and MALAT1 expression were significantly elevated in ER/PR-negative and human epidermal growth factor receptor 2 (HER2)-positive cases, cancers that are associated with poor prognosis and high metastatic potential." (PMID 40674376, 2025). "Western blotting analysis revealed that the upregulation of Nanog, OCT4, and SOX2 was observed in breast cancer cells that exhibited overexpression of SNORA47, whereas a downregulation of these markers was evident in cells treated with ASOs targeting SNORA47." (PMID 40264043, 2025). "The MCF-7 mammary cancer cell line only exhibited an increased expression of SOX2, whereas the MDA-MB231 cell line only exhibited an increased expression of CD44." (PMID 40362259, 2025). "Hormone receptors: In breast cancer, SOX2 and MALAT1 were upregulated in ER/PR-negative and HER2-positive cases, reflecting their association with more aggressive phenotypes." (PMID 40674376, 2025). "Yet SOX2 amplification and subsequent overexpression have also been shown in a variety of malignancies, including breast cancer, gastric cancer, and prostate cancer, raising the possibility that SOX2 is an oncogene." (PMID 39192657, 2025).
breast cancer (continued). "To confirm that KIF20A regulates breast cancer stemness, we assessed the expression of canonical stem cell markers (Oct4, Sox2, or NANOG) and found that KIF20A siRNA transfection led to decreased mRNA levels of these markers in Hs578T cells." (PMID 41392981, 2025). "ITCH knockdown increased the level of GATAD2B, but also elevated the mammosphere formation of breast cancer cells and increased cancer stem cell factors SOX2 and c-Myc." (PMID 40136647, 2025). "In contrast, in the MDA-MB-231 cell line, a highly malignant breast cancer cell line, Oxamate treatment decreased Sox2 and E-cadherin expression, while Nanog and N-cadherin expression remained unchanged." (PMID 40565174, 2025). "This suggests a more complex and multifaceted interaction between SOX2OT and SOX2 in tamoxifen-resistant breast cancer." (PMID 38649821, 2024). "Breast malignant tumors exhibit high expression of stemness-related genes, including SOX2, OCT4, and NANOG in CSCs." (PMID 38802335, 2024). "The SHH-GLI1 pathway related lncRNA-Hh can strengthen CSC generation in breast cancer via activating the Hedgehog signaling and increasing the expressions of downstream targets SOX2 and OCT4." (PMID 38254782, 2024). "In RNA-sequencing data from The (TCGA) database, a positive correlation between the expression of NSDHL and SOX2 was found in luminal-type breast cancer specimens (n = 998)." (PMID 39516821, 2024). "SMS2 decreased the CD24 transcription level but increased the transcription levels of stemness-related genes including CD44, ALDH, OCT 4 and SOX2 in breast cancer cells." (PMID 38285090, 2024). "SOX2 is an oncogene in all breast cancer subtypes and its expression correlates with breast cancer aggressiveness." (PMID 38755629, 2024). "LINC00511 has a role in the stemness of breast cancer cells since it stimulates the sphere-formation and the expression of stem factors such as Nanog, SOX2, and OCT4 and facilitates CSC features." (PMID 39170516, 2024). "Through activating the Wnt/β-catenin pathway, SOX2 induces EMT in breast cancer and prostate cancer." (PMID 38331879, 2024). "In our study, OLE-mALG treatment resulted in increased expression of pluripotency and stemness genes CSCs (27-fold OCT3-4, 10-fold NANOG, 4-fold SOX2) in the 3D model of breast cancer." (PMID 38722566, 2024). "MiR-145-5p can inhibit tumor growth, as well as distal metastasis in breast cancer by targeting SOX2." (PMID 39039505, 2024). "For instance, in breast cancer, the downregulation of miRNA-140 promotes proliferation and inhibits apoptosis by influencing SOX2 expression." (PMID 38285101, 2024). "Iadademstat (ORY-1001) is a highly potent LSD1 inhibitor that suppressed enhancer-driven activation of SOX2 in BT-474 breast cancer cells." (PMID 38612911, 2024). "Real-time PCR analysis showed that SMS2 decreased CD24 transcription level but increased the transcription levels of stemness-related genes including CD44, ALDH, OCT 4 and SOX2 in breast cancer cells (P < 0.05)." (PMID 38285090, 2024). "In breast cancer, the patients whose tumors were enriched with embryonic stem cell genes, like SOX2, Nanog, and OCT4, had significantly worse overall survival compared to those with a non-stem-cell genotype." (PMID 38612911, 2024). "As a partner of Oct4, Nanog regulates the transcription factor SOX2 to enhance the stemness of breast cancer cells." (PMID 38612715, 2024). "In lung cancer, CDK1 drives SOX2 to maintain tumor cell stemness 34, and similar conclusions have been made in glioma and breast cancer 35,36." (PMID 38164286, 2024). "Targeting SOX-2 driven cancer stem cells has demonstrated the clinical promise of iadademstat as an anti-ti-SOX2 epigenetic breast cancer treatment, especially in the SOX2-rich luminal-B HER2+ type." (PMID 36810560, 2023).
breast cancer (continued). "In head and neck, and breast cancer, it has been reported that the radioresistance induced by GDF15 is linked to the expression of stemness markers (CD44, Sox2, and Nanog) and the ability of cancer cells to form spheroids." (PMID 38201456, 2023). "Iadademstat treatment of patients with luminal-B breast cancer and mammospheres significantly reduced SOX2 expression, suggesting the selective targeting of SOX2-driven CSCs." (PMID 36810560, 2023). "STEMVAC is a multi-Ag plasmid DNA vaccine encoding Th1 epitopes of CD105, Yb-1, SOX2, CDH3, and MDM2: five important TAAs associated with cancer stem cells and the EMT process in breast cancer." (PMID 36679991, 2023). "SOX2, NANOG, OCT3/4, as well as a CD44+/CD24−/low phenotype were reported to be the principal markers associated with stemness in breast cancer." (PMID 37446326, 2023). "SOX2 has been previously reported to function as an oncogene in various cancers, including breast cancer, prostate cancer, renal cell carcinoma and thyroid cancer." (PMID 37957698, 2023). "Previous studies also demonstrated that expression levels of OCT4, NANOG, and SOX2 were higher in poorly differentiated tumors than that of well-differentiated breast cancers, glioblastomas, and bladder carcinomas as well as OSCC." (PMID 37109090, 2023). "TUNA was found to be increased in human breast cancer tissues, and in vitro experiments on human breast cancer cell lines suggest that TUNA promotes oncogenic activity through the expression of SOX2 and promotion of epithelial-to-mesenchymal transition." (PMID 37325564, 2023). "Specifically in breast cancer, SOX2 has been shown to be involved in the development of breast CSCs (BCSC)." (PMID 37614497, 2023). "In breast cancer, CD44ICD induces the transcription of stemness factors such as Nanog, Sox2, and Oct-4, thereby contributing to breast cancer aggressiveness and tumorigenesis." (PMID 37568628, 2023). "Our findings revealed a gradual increase in the mRNA expression levels of stemness-related markers, OCT4 and SOX2, in breast cancer cells over time." (PMID 38037058, 2023). "Stable silencing of SOX2 oncoprotein via overexpression of DNMT3A in mice retarded the tumorigenic phenotype of breast cancer cells." (PMID 35620052, 2022). "To further explore the model, we analysed other stemness characteristics in MCF7 and MDA-MB-231 breast cancer cell lines, corroborating that SOX2-high cells were more metabolically active, proliferative, migratory, invasive, and drug-resistant." (PMID 36566021, 2022). "Octamer-binding transcription factor 4 (OCT4) and sex-determining region Y-box 2 (SOX2) are considered to be promising BCSC markers, whose expression is closely associated with multi-drug resistance in breast cancer." (PMID 35402219, 2022). "Upregulated SOX2 proteins induce chemoresistance in breast cancer cells and promote their stemness property through the recruitment of regulatory T cells (Tregs) to the tumor microenvironment." (PMID 35906698, 2022). "A previous study demonstrated that SOX2 reduces breast cancer cell sensitivity to TAM by activating Wnt signaling." (PMID 36601474, 2022). "Another study has also demonstrated that upregulation of miR-590-5p impedes breast cancer progression involving with suppression of cell migration and proliferation via regulating SOX2." (PMID 35310934, 2022). "We next examined the role of activated macrophages in regulation of CSC phenotype by examining the expression of CSC specific transcriptional factors Sox-2, Oct3/4 and Nanog in breast cancer cells by western blotting, q-PCR and immunofluorescence." (PMID 35300689, 2022). "OCT4 and SOX2 correlated with poor differentiation, more advanced stage, and worse prognosis in breast cancer patients." (PMID 35402219, 2022).
breast cancer (continued). "SOX2 also activates Tregs by interacting with C-C motif chemokine 1, leading to breast cancer cell stemness." (PMID 35402219, 2022). "ID4 has been shown to promote chemo-resistance and stemness of glioma cells by promoting SOX2 expression, but has yet to be studied in the context of breast cancer resistance." (PMID 36291790, 2022). "Meanwhile, another study found that curcumin inhibited the expression of Oct4 and Sox2 by suppressing Hedgehog/Gli1 pathways in breast cancer MDA-MB-231 and MDA-MB-468 cells." (PMID 36009200, 2022). "For example, Sox2‐overexpressed breast cancer cells exhibit downregulated AMPK signalling and activated mTOR to maintain their cancer stem‐like phenotypes." (PMID 36114703, 2022). "Tumor-associated macrophages upregulated the expression of SOX2 and promoted CSC-like phenotypes in breast cancer cells." (PMID 35465267, 2022). "The abnormal expression of SOX2 has been reported in many types of cancer, including lung cancer, breast cancer, colorectal cancer, and bladder cancer." (PMID 36293387, 2022). "SOX2 is a cancer stem cell marker that is highly expressed in breast cancer stem cells and mediates resistance to chemotherapy." (PMID 36601474, 2022). "In breast cancer, SOX2 appears to act as a functional downstream AKT target, with a direct physical interaction between the two proteins." (PMID 36118530, 2022). "For example, SOX2 has been shown to regulate multiple malignant processes of breast cancer through the SOX2/miR-181a-5p, miR-30e-5p/TUSC3 axis." (PMID 35321017, 2022). "The specific down-regulation of SOX2 by actinomycin D leads to depletion of CSCs, blocking the tumour-initiating capacity of breast cancer stem cells." (PMID 36566021, 2022). "This is the case for gastric and breast cancer, where the altered expression of this lncRNA results in the regulation of the transcription factors SOX2, OCT4, and NANOG." (PMID 35954194, 2022). "In the present study, OCT4 and SOX2 expressions were detected in breast cancer tissues to explore their correlations with tumor features and prognosis in breast cancer patients." (PMID 35402219, 2022). "VEGF can bind to VEGF receptor 2 (VEGFR2) to activate the STAT3 pathway as well as to increase Myc and Sox-2 expression to enhance the stemness of the breast cancer cells." (PMID 35805056, 2022). "(2014) showed that SOX2 is upregulated in TAM-R breast cancer cells and promotes breast cancer resistance to TAM." (PMID 36601474, 2022). "The EGF secreted by the TAMs activates the EGFR/ STAT3/SOX‐2 paracrine pathway in the breast cancer, resulting in increased SOX‐2 expression, which in turn enhances the CSC phenotype in the tumor cells." (PMID 34914196, 2022). "In conclusion, FGFR2, RET, ERBB4, MMP16, FN1, and SOX2 are potential targets of HON for overcoming TAM resistance in breast cancer." (PMID 36601474, 2022). "Sox2 is a pluripotency TF that has been reported as being highly expressed in breast cancer tissues." (PMID 35326385, 2022). "SOX2OT was reported to upregulate SOX2 substantially and augment breast cancer cell growth, whereas knockdown of SOX2OT impeded SOX2 transcription in bladder cancer." (PMID 35415876, 2022). "For instance, miR-145-5p induces tumor cell apoptosis in prostate cancer by degrading WIP1; MiR-145-5p is extremely decreased in breast cancer and attenuates paclitaxel resistance and suppresses the progression of breast cancer cells by targeting SOX2." (PMID 36214767, 2022). "We found that Mir145 was significantly downregulated in ATF3-induced mammary tumors, and that its direct targets Klf4 and Sox2 were significantly upregulated." (PMID 33652981, 2021). "For instance, Oct4, Sox2, or Nanog upregulation facilitates the expansion features of breast cancer stem cells and promotes breast cancer tumorigenesis, and KLF family members have always been recognized as oncogenes in multiple tumors." (PMID 34601500, 2021).
breast cancer (continued). "Alternatively, miR-200c-3p modulates the expression of metabolic enzyme cytochrome P450 1B1 (CYP1B1) and transcription factor SOX2 in renal cell carcinoma and breast cancer, respectively." (PMID 34439151, 2021). "IL20RA increases the SP and ALDHbr proportions of breast cancer cells, enhances the sphere formation ability, and promotes the expression of core stemness genes, such as Sox2 and Oct4, as well as increases chemoresistance of breast cancer cells." (PMID 33456560, 2021). "For example, SOX21‐AS1 modulates breast cancer stem cells properties and carcinogenesis via targeting SOX2." (PMID 33103351, 2021). "The literature provides data on validated targets, such as KRAS for miR-181c-5p, or SOX2 for miR-625-5p, which are important oncogenes in breast cancer." (PMID 34439180, 2021). "In terms of other tumour entities, a prognostic correlation of SOX2 in colon cancer, breast cancer, and HNSCC is well-documented." (PMID 33009929, 2021). "It has been recently demonstrated that SOX2, a transcription factor essential for the maintenance of proliferation and self-renewal of cancer stem cells, is related to breast cancer initiation." (PMID 33863935, 2021). "A recent comparative analysis demonstrated that in patients with breast cancer, a hypomethylation signature (OCT4, SOX2, NANOG and SIN3A) in CTC clusters is associated with poor progression-free survival." (PMID 34830995, 2021). "Correspondingly, ectopic lnc408 obviously augmented both mRNA and protein expressions of breast cancer stemness markers (e.g., SOX2, Nanog, and CD44)." (PMID 33934099, 2021). "TAM was also found to promote CSC phenotype and tumorigenesis in breast cancer by activating the EGFR/Stat3/Sox-2 signaling pathway, while inhibition of Sox2 mitigates TAM mediated induction of CSC phenotype and breast tumor growth." (PMID 34207035, 2021). "lncRNA PVT1 has been demonstrated for upregulating SOX2 levels (sex-determining region Y box) and critically propagating breast cancer." (PMID 34391433, 2021). "SOX2-dependent activation of Wnt signaling in tamoxifen-resistant breast cancer cells leads to the increase of CSC content." (PMID 34768751, 2021). "In fact, increased extracellular matrix stiffness has also been associated with increased resistance to chemotherapeutic drugs of breast cancer cells and with elevated expression of Sox2 and other stem cell factors in hepatocellular carcinoma." (PMID 34071397, 2021). "We found that the resulting peptide (SOX2-iPep) possessed intrinsic cell penetration and promising nuclear localization into breast cancer cells, and decreased cellular proliferation of SOX2 overexpressing cell lines." (PMID 34502261, 2021). "Genes related to proliferation (MKI67, CCNA2), differentiation (EPCAM, CDH1), epithelial to mesenchymal transition (VIM, SNAI2), pluripotency and breast cancer stem cells (SOX2, NANOG, CD44) were included." (PMID 34090457, 2021). "In breast cancer, Sox2+ cancer cells, via activation of nuclear factor of activated T-cells (NFAT), STAT3 and NF-κB, express chemokines CCL3 and ICAM-1 and thus recruit TAMs into the TME." (PMID 34235155, 2021). "The complex network governing coupregulation of Oct4, Sox2, and Nanog is also noted in many human CSCs derived from renal cell carcinoma, hepatocellular carcinoma, breast cancer, and lung cancer." (PMID 34349823, 2021). "Of interest, we previously found that the transcription activity of Sox2 correlates with its level of phosphorylation in breast cancer cells." (PMID 34287231, 2021). "Overexpression of SOX2 in MCF-7 breast cancer cells has also been shown to increase cell proliferation and tumorigenesis by upregulating cyclin D1 and subsequently facilitating G1/S cell cycle transition." (PMID 34436030, 2021). "For example, treatment of breast cancer cells with conditioned medium of TAMs leads to increments in the stem cell markers Sox-2, Oct3/4 and Nanog with enhanced ALDH1 activity in a mouse model." (PMID 34235155, 2021).